ANKRD20A2P (ankyrin repeat domain 20 family member A2, pseudogene)
Synonyms: formerly ANKRD20A2
Gene: Transcribed unprocessed pseudogene on chromosome 9 (40,223,397 to 40,292,345, forward strand). Ensembl gene ENSG00000183148.
Genetic constraint (gnomAD): Loss-of-function variants: 1 observed, 3.14 expected, observed/expected ratio (o/e) 0.32, 90% interval 0.11 to 1.42. That is too few expected variants to judge how well the gene tolerates losing a copy. Missense variants: 1 observed, 41.64 expected, observed/expected ratio (o/e) 0.024, 90% interval 0.008 to 0.11. Synonymous variants: 1 observed, 11.63 expected, observed/expected ratio (o/e) 0.086, 90% interval 0.03 to 0.41.